EBF4 (EBF transcription factor 4)
Description:
Transcription factor. Binds to specific sequence motif 5'-CCCNNG[GA]G-3' in regulatory elements of putative target immunoregulatory genes such as NKG7, GZMA, and TBX21. Positively modulates transcription of NKG7. May play a role in regulating FAS/CD95-mediated apoptosis in cytotoxic NK cells and T-cells, probably downstream of interleukin IL2 signaling.
Synonyms: O/E-4; OE-4; COE4; KIAA1442; RP5-860F19.3
Tractability: PROTAC: ubiquitination databases record sites on it.
Gene: Protein-coding gene on chromosome 20 (2,692,780 to 2,760,108, forward strand). Ensembl gene ENSG00000088881.
Subcellular location: Nucleus
Gene Ontology:
Molecular function: DNA-binding transcription factor activity, RNA polymerase II-specific; DNA-binding transcription factor binding; protein binding; RNA polymerase II cis-regulatory region sequence-specific DNA binding; DNA binding; DNA-binding transcription activator activity, RNA polymerase II-specific; DNA-binding transcription factor activity; RNA polymerase II transcription regulatory region sequence-specific DNA binding
Biological process: positive regulation of transcription by RNA polymerase II; T cell apoptotic process; regulation of transcription by RNA polymerase II; regulation of DNA-templated transcription
Cellular component: chromatin; nucleus
Genetic constraint (gnomAD): Loss-of-function variants: 32 observed, 49.54 expected, observed/expected ratio (o/e) 0.65, 90% interval 0.49 to 0.87. The synonymous counts are far from expectation, so gnomAD's model fits this gene poorly and the ratio says little. Missense variants: 823 observed, 689.2 expected, observed/expected ratio (o/e) 1.19, 90% interval 1.13 to 1.26. Synonymous variants: 385 observed, 296.73 expected, observed/expected ratio (o/e) 1.3, 90% interval 1.19 to 1.41.
Homologues: Orthologues: chimpanzee EBF4 (99% identical), macaque EBF4 (99% identical), pig EBF4 (98% identical), dog EBF4 (98% identical), mouse Ebf4 (95% identical), rat Ebf4 (95% identical), rabbit EBF4 (92% identical), guinea pig EBF4 (91% identical), tropical clawed frog coe3l (71% identical), Drosophila melanogaster kn (55% identical), Caenorhabditis elegans unc-3 (46% identical). Paralogues in human: EBF3 (74% identical), EBF1 (72% identical), EBF2 (69% identical).
Diseases named in the same sentence as EBF4 in open-access papers:
EBF4 is named in the same sentence as 8 diseases in open-access papers, as found by Europe PMC text mining. Sharing a sentence is not in itself a finding about the gene and the disease. The quoted sentences say what the papers report.
acute coronary syndrome (1 paper, 2023). Signs and symptoms related to acute ischemia of the myocardium secondary to coronary artery disease. "They found higher methylation at cg05825244 in EBF4 (among our 12 CpGs differentially methylated in VLBW adults), which was associated with a 23% increased risk of acute coronary syndromes." (PMID 36959629, 2023).
trisomy 21 (1 paper, 2023). A chromosomal disorder consisting of the presence of an extra chromosome 21. "Methylation of members of this gene family have been associated with a number of phenotypes, including EBF4 methylation associated with hematopoiesis and neuronal development in persons with Trisomy 21, and EBF1 and EBF3 methylation to neurobehavioral development in very preterm infants." (PMID 36959629, 2023).
cancer (3 papers, 2010 to 2021). A tumor composed of atypical neoplastic, often pleomorphic cells that invade other tissues. "A few candidate genes, such as ZBTB21, MTSS2, and EBF4, still have elusive functional mechanisms, while belonging to families of genes with suggested roles in cancer susceptibility." (PMID 34067022, 2021). "Little research has been done on the role of EBF4 in cancer, and a few evidences suggest that it plays important roles in neural development and B-cell maturation." (PMID 33962398, 2021).
tumor (1 paper, 2021). "As for tumor grade, we combined Grades 1 and 2 and observed that the expression of EBF1, EBF2, and EBF4 increased in Grade 3 tumors, in comparison with Grades 1 and 2 (all P<0.001)." (PMID 34100918, 2021).
EBF4 also shares sentences with these, for which no sentence is quoted: Barrett esophagus (1 paper); breast carcinoma (1); infection (1); Obesity (1).